GSX1 (GS homeobox 1)
Description:
Probable transcription factor that binds to the DNA sequence 5'-GC[TA][AC]ATTA[GA]-3'. Activates the transcription of the GHRH gene. Plays an important role in pituitary development.
Synonyms: GSH1; Gsh-1
Tractability: No criterion of Open Targets' tractability assessment is met for any kind of drug.
Gene: Protein-coding gene on chromosome 13 (27,792,483 to 27,794,768, forward strand). Ensembl gene ENSG00000169840.
Subcellular location: Nucleus
Subcellular location (Human Protein Atlas): Golgi apparatus; Cytosol; Nucleoplasm
Gene Ontology:
Molecular function: protein binding; sequence-specific DNA binding; sequence-specific double-stranded DNA binding; DNA-binding transcription factor activity, RNA polymerase II-specific; RNA polymerase II cis-regulatory region sequence-specific DNA binding; DNA binding; DNA-binding transcription activator activity, RNA polymerase II-specific; DNA-binding transcription factor activity
Biological process: positive regulation of transcription by RNA polymerase II; brain development; central nervous system development; neuron differentiation; regulation of DNA-templated transcription
Cellular component: chromatin; nucleus
Genetic constraint (gnomAD): Loss-of-function variants: 13 observed, 14.55 expected, observed/expected ratio (o/e) 0.89, 90% interval 0.58 to 1.42. The synonymous counts are far from expectation, so gnomAD's model fits this gene poorly and the ratio says little. Missense variants: 371 observed, 335.55 expected, observed/expected ratio (o/e) 1.11, 90% interval 1.01 to 1.21. Synonymous variants: 202 observed, 158.43 expected, observed/expected ratio (o/e) 1.27, 90% interval 1.14 to 1.43.
Homologues: Orthologues: chimpanzee GSX1 (100% identical), macaque GSX1 (99% identical), pig GSX1 (98% identical), dog GSX1 (98% identical), rabbit GSX1 (98% identical), mouse Gsx1 (97% identical), rat Gsx1 (96% identical), zebrafish gsx1 (69% identical), tropical clawed frog not (19% identical), Caenorhabditis elegans ceh-100 (19% identical), Caenorhabditis elegans ceh-99 (13% identical). Paralogues in human: NOTO (21% identical).
Diseases named in the same sentence as GSX1 in open-access papers:
GSX1 is named in the same sentence as 19 diseases in open-access papers, as found by Europe PMC text mining. Sharing a sentence is not in itself a finding about the gene and the disease. The quoted sentences say what the papers report.
Obesity (2 papers, 2021). Accumulation of substantial excess body fat. "Of note, GSX1 methylation levels have been linked to obesity-associated CRC." (PMID 34070516, 2021).
Anosmia (1 paper, 2022). An inability to perceive odors. "We have identified a gene regulatory network, Gsx1/2 – Dlx1/2/5/6 – GAD2/1/Sp8/Sp9 – Tshz1 – Prokr2, which governs OBiN development; mutations of some of these genes result in human Kallmann syndrome with abnormal olfactory function (anosmia or hyposmia)." (PMID 34374948, 2022).
astrocytoma (1 paper, 2025). "Collectively, these results support a role for GSX1+ cluster in IDH-mutant astrocytoma malignant progression, with potential implications for developing targeted therapies against this aggressive tumor subtype." (PMID 41460424, 2025). "While our study provides novel insights into the GSX1+ subpopulation in IDH-mutant astrocytoma, several limitations warrant consideration." (PMID 41460424, 2025). "Single-cell RNA sequencing analysis identified a distinct GSX1+ cluster (Cluster 7) enriched in high-grade IDH-mutant astrocytoma." (PMID 41460424, 2025). "Through single-cell RNA sequencing, we identified a distinct GSX1+ tumor subpopulation specifically enriched in high-grade IDH-mutant astrocytoma (WHO grades 3–4), localized at the pseudotime trajectory terminus and associated with poor prognosis and immunosuppressive phenotype." (PMID 41460424, 2025). "Our identification of GSX1+ clusters in high-grade IDH-mutant astrocytoma aligns with its broader role in fate determination and malignancy, suggesting conserved mechanisms whereby GSX1 may drive aggressive phenotypes through aberrant differentiation or synaptic signaling pathways." (PMID 41460424, 2025).
cervical cancer (1 paper, 2024). A primary or metastatic malignant neoplasm involving the cervix. "Detecting the methylation of the DPP6, RALYL, and GSX1 genes was also used for the early diagnosis of cervical cancer in women in Stockholm, Sweden." (PMID 39766341, 2024).
colorectal carcinoma (1 paper, 2025). A malignant epithelial neoplasm that arises from the colon or rectum and invades through the muscularis mucosa into the submucosa. "Among the syntenic blocks between these regions, CDX2, CDK8, GSX1, and PDX1 are among candidate colorectal carcinoma and/or cancer driver genes affected by these recurrently gained chrs between human and mouse." (PMID 41051921, 2025).
schizophrenia (1 paper, 2024). A major psychotic disorder characterized by abnormalities in the perception or expression of reality. "In addition, studies have shown that zebrafish without gsx1-expressing neurons and mouse Gsx1 KOs have disrupted pre-pulse inhibition (PPI), a sensory gating behavior often disrupted in neurodevelopmental disorders (NDDs) such as schizophrenia." (PMID 38669217, 2024).
tumor (3 papers, 2020 to 2025). "High TPS was associated with genes such as SOX11 and GSX1, which may promote tumour proliferation, whereas Low TPS was enriched with immune-related genes like LILRB4, highlighting the complex interactions within the tumour microenvironment." (PMID 39457550, 2024). "GSX1 and SOX11 have been identified as critical marker genes for the High TPS group, indicating their significant influence on tumour dynamics." (PMID 39457550, 2024).
cancer (2 papers, 2024 to 2025). A tumor composed of atypical neoplastic, often pleomorphic cells that invade other tissues. "GSX1 plays a critical role in regulating neural progenitor cells, consequently aiding in the maintenance of cellular stemness and differentiation, which enhances the complexity and adaptability of cancer cells." (PMID 39457550, 2024).
neurodevelopmental disorder (1 paper, 2024). A behavioral and cognitive disorder with onset during the developmental period that involves impaired or aberrant development of intellectual, motor, or social functions. "Gsx1-expressing neurons in the larval zebrafish brainstem modulate processing of acoustic stimuli in a behavioral testing paradigm related to sensory motor gating endophenotypes associated with neurodevelopmental disorders in humans." (PMID 38669217, 2024).
GSX1 also shares sentences with these, for which no sentence is quoted: nematode infection (2 papers); cyst (1); esophageal squamous cell carcinoma (1); fungal infections (1); infection (1); Kallmann syndrome (1); liver cancer (1); malignant glioma (1); mastitis (1); spinal cord injury (1).